RN7SL314P (RNA, 7SL, cytoplasmic 314, pseudogene)
Gene: Miscellaneous RNA gene on chromosome 10 (37,297,398 to 37,297,689, forward strand). Ensembl gene ENSG00000244402.
Homologues: Orthologues: chimpanzee Metazoa_SRP (99% identical), macaque Metazoa_SRP (90% identical), macaque Metazoa_SRP (89% identical). Paralogues in human: RN7SL2 (74% identical), RN7SL1 (73% identical), RN7SL126P (72% identical), RN7SL444P (72% identical), RN7SL586P (72% identical), RN7SL709P (72% identical), RN7SL246P (72% identical), RN7SL3 (72% identical), RN7SL769P (72% identical), RN7SL788P (71% identical), RN7SL88P (71% identical), RN7SL220P (71% identical), and 706 more.